C2CD4C (C2 calcium dependent domain containing 4C)
Synonyms: FAM148C; KIAA1957; NLF3
Tractability: No criterion of Open Targets' tractability assessment is met for any kind of drug.
Gene: Protein-coding gene on chromosome 19 (405,443 to 409,147, reverse strand). Ensembl gene ENSG00000183186.
Subcellular location (Human Protein Atlas): Primary cilium; Vesicles; Basal body; Microtubules; Primary cilium tip
Gene Ontology:
Cellular component: cytosol
Genetic constraint (gnomAD): Loss-of-function variants: 5 observed, 5.02 expected, observed/expected ratio (o/e) 1, 90% interval 0.51 to 1.8. That is too few expected variants to judge how well the gene tolerates losing a copy. Missense variants: 664 observed, 561.25 expected, observed/expected ratio (o/e) 1.18, 90% interval 1.11 to 1.26. Synonymous variants: 364 observed, 263.6 expected, observed/expected ratio (o/e) 1.38, 90% interval 1.27 to 1.51.
Homologues: Orthologues: chimpanzee C2CD4C (99% identical), rat C2cd4c (91% identical), mouse C2cd4c (90% identical), pig C2CD4C (88% identical), dog C2CD4C (88% identical), guinea pig C2CD4C (74% identical), tropical clawed frog c2cd4c (61% identical), zebrafish C2CD4C (56% identical). Paralogues in human: C2CD4D (31% identical), C2CD4B (30% identical), C2CD4A (28% identical), SYT6 (17% identical), RPH3A (17% identical), SYT10 (16% identical), SYT9 (16% identical), SYT3 (16% identical), SYTL4 (15% identical), SYT1 (15% identical), SYT2 (15% identical), SYT11 (14% identical), and 19 more.